ALK (ALK receptor tyrosine kinase)
Diseases named in the same sentence as ALK in open-access papers (continued):
Sharing a sentence is not in itself a finding about the gene and the disease.
lung cancer (continued). "The author of this article is an ALK‐positive lung cancer patient with a background in cancer research and education." (PMID 41213866, 2025). "In order to explore the molecular processes facilitating the survival of ALK-driven lung cancer cells under the influence of CAFs, differential gene expression analysis between treated mono- and co-culture conditions was performed." (PMID 40524253, 2025). "Subsequently, next-generation sequencing involving 68 lung cancer-related genes identified an EML4 (exon 6):: ALK (exon 20) gene fusion(V3)." (PMID 40224190, 2025). "The International Association for the Study of Lung Cancer recommends, at a minimum, testing for EGFR, ALK, and ROS1." (PMID 41153394, 2025). "Lung cancer BM, for instance, frequently retains genetic alterations characteristic of the primary lung cancer, such as EGFR mutations and ALK rearrangements observed in non-small cell lung cancer." (PMID 39857798, 2025). "In lung cancer, anaplastic lymphoma kinase (ALK) was detected in 14% (17/118), and c-MET was detected in 61% (78/128)." (PMID 40075672, 2025). "In this study, we report a non-canonical role of human secretory ribonuclease 1 (RNase1), which binds to and activates wild-type ALK in lung cancer cells, thereby triggering its downstream signaling pathway." (PMID 40246819, 2025). "In our study, the safety profile of crizotinib was better compared to previous studies involving ROS1-positive and ALK-positive lung cancer individuals." (PMID 40142301, 2025). "In 2011, ALK-TKIs were approved by the FDA as the first line therapy for ALK positive lung cancer patients." (PMID 40853979, 2025). "In recent years, new treatments called tyrosine kinase inhibitors (TKIs) have been developed to target specific genetic mutations in lung cancer, such as EGFR and ALK." (PMID 41149462, 2025). "Clinical data analysis further revealed that co-expression of RNase1 and ALK strongly correlated with poorer survival outcomes in lung cancer patients." (PMID 40246819, 2025). "In nonsmall cell lung cancer (NSCLC), various genetic aberrations have been studied for their association with VTE, including ALK fusions, KRAS mutations, and EGFR mutations." (PMID 39851266, 2025). "The EML4‐ALK fusion is the most common ALK rearrangement in non‐small cell lung cancer, and multiple ALK tyrosine kinase inhibitors have been approved." (PMID 40904239, 2025). "The same analysis reported the common features of the associated lung cancer, including the adenocarcinoma pathology and at least one driver mutation in nearly half of the cases, including KRAS, EGFR, ALK, BRAF, and ATM." (PMID 41476748, 2025). "Researchers have only reported a small number of lung cancers with intestinal metastasis, including few ones with ALK rearrangement, but most of them are ADC subtypes instead of PLCs." (PMID 40224190, 2025). "Studies on ALK-TKIs for NSCLC are predominantly published in journals such as Lung Cancer, Journal of Thoracic Oncology, and Frontiers in Oncology." (PMID 40894217, 2025). "Anaplastic lymphoma kinase (ALK) fusion‐positive lung cancer represents approximately 3%–7% of NSCLC cases." (PMID 40151836, 2025). "Lung cancer etiology generally involves multiple mechanisms, like ALK (anaplastic lymphoma kinase) gene rearrangement, and current treatments are based on such tumor-specific changes." (PMID 41008962, 2025). "The main aim of this review is to provide readers with the current knowledge and understanding of ALK‐positive lung cancer and its treatment." (PMID 41213866, 2025). "A high rate of intratumoral heterogeneity is also common for ALK rearrangements in lung cancer, PTEN deletion in prostate cancer, as well as BRAF mutation in pulmonary adenocarcinoma." (PMID 40227771, 2025).
lung cancer (continued). "Based on these findings, the U.S. Food and Drug Administration approved alectinib (Alecensa) as the first adjuvant treatment for patients with ALK-positive early-stage lung cancer in April 2024." (PMID 41303058, 2025). "The review concludes with an analysis of various therapeutic approaches to treat ALK‐positive lung cancer." (PMID 41213866, 2025). "Radiomic features of another less-used imaging modality in lung cancer—that of MRI for brain metastases—have also been used to predict specific genetic mutations, such as EGFR, ALK, and KRAS, with AUC of over 0.9, as well as OS." (PMID 40075729, 2025). "Treatments are mostly available for the metastatic stage, but we will also discuss adjuvant therapy for EGFR mutations and ALK fusions, as well as stage III post-chemoradiotherapy treatment for EGFR lung cancer." (PMID 40136350, 2025). "Combining PI3K inhibitors with other targeted agents, such as EGFR tyrosine kinase inhibitors or ALK inhibitors, can help overcome resistance in specific lung cancer subtypes." (PMID 39953539, 2025). "We report a rare case of a 14-year-old girl, whose father and grandfather both had lung cancer, diagnosed with advanced, multi-site metastatic ALK-positive NSCLC." (PMID 40786512, 2025). "Key advancements underscore this shift: molecularly targeted drugs (e.g., trastuzumab for HER2-positive breast cancer, EGFR and ALK inhibitors for lung cancer) have improved efficacy and reduced toxicity compared to conventional therapy." (PMID 41295218, 2025). "In 2013, the results of the trial PROFILE 1007 with an oral ALK TKI crizotinib were published for advanced ALK-positive lung cancer, comparing crizotinib to the usual standard-of-care chemotherapy." (PMID 40136350, 2025). "Despite such significant therapeutic advances, major challenges persist in the management of patients with ALK+ lung cancer." (PMID 40674592, 2025). "Second, it demonstrates that high PD-L1 expression has limited predictive value for ICI monotherapy in ALK-positive lung cancer." (PMID 41487577, 2025). "The samples obtained through EBUS-TBNA demonstrated solid quality parameters for RNA, which is crucial in lung cancer, given the therapeutic implications of certain fusions like ALK and ROS1." (PMID 40361881, 2025). "Alectinib, a 2nd-generation anaplastic lymphoma kinase–tyrosine kinase inhibitor (ALK-TKI), is an established 1st-line therapy for advanced ALK fusion gene–positive non–small cell lung cancer (NSCLC)." (PMID 41036487, 2025). "In 1,076 formalin-fixed paraffin-embedded lung cancer samples, SplitFusion identified novel fusions and revealed that EML4::ALK variant 3 was associated with multiple fusion variants coexisting in the same tumor." (PMID 40041857, 2025). "Resistance to ALK-targeted therapy in lung cancer is also related to immune escape mechanisms involving immune checkpoints." (PMID 40873540, 2025). "Female, family history of lung cancer, positive driver genes, and first-line use of second-generation ALK-TKIs are independent prognostic factors in young patients with advanced NSCLC." (PMID 41002559, 2025). "We herein presented a rare case of ALK-positive lung cancer that responded to ICI monotherapy as the 8th-line treatment." (PMID 40660550, 2025). "The analysis of human ALK-rearranged lung cancer samples also found that some LUADs present squamous features, indicating a tendency towards squamous transformation." (PMID 40568576, 2025). "Compared to the 39% of patients’ samples with driver mutations and alterations who underwent sequencing of lung carcinomas at our institution, 76% of patients with CNS metastases harbored driver mutations and alterations, predominantly EGFR, KRAS, and ALK." (PMID 40423053, 2025). "Clinicopathologic and molecular features of ALK-rearrangement lung carcinomas with small intestinal metastases." (PMID 40224190, 2025).
lung cancer (continued). "Consistent with its role as an oncogenic driver, full‐length ALK and ALK translocations are found in primary solid tumors including neuroblastoma and lung carcinoma." (PMID 40387841, 2025). "On the contrary, lung carcinoma, while also subject to personalized approaches with drugs targeting EGFR mutations or ALK rearrangements and immunotherapy, generally shows lower overall response rates to chemotherapy compared to breast cancer." (PMID 40558249, 2025). "NSCLC with ALK rearrangements is a subtype of lung cancer with specific clinical and pathological features." (PMID 38605928, 2024). "Originally identified in anaplastic large cell lymphomas, ALK alterations are now also recognized in various solid tumors, including lung cancers." (PMID 39199653, 2024). "In summary, this study is the first to examine real-world treatment patterns and outcomes for lung cancer patients in Ontario who received one or more ALK TKI therapies across any line of treatment at a population level." (PMID 39851929, 2024). "Most patients with lung cancers harboring NTRK gene fusions exhibit clinical characteristics similar to those with ALK, RET, or ROS1 fusions, and are often found in a younger population with minimal or no smoking history." (PMID 39199653, 2024). "The most usual abnormality of ALK that occurs in lung cancer is ALK rearrangement so 3% to 5% of lung cancer patients have ALK rearrangement." (PMID 38234663, 2024). "Lung cancer is a prevalent malignancy, with the rearrangement of the anaplastic lymphoma kinase (ALK) gene being responsible for a minority of cases of non-small cell lung cancer (NSCLC)." (PMID 39555099, 2024). "Understanding resistance mechanisms, adopting liquid biopsies, and exploring diverse treatment strategies mark crucial steps toward managing ALK+ lung cancer as a chronic condition." (PMID 38397899, 2024). "The US Food and Drug Administration has recommended crizotinib for the treatment of ALK fusion-positive lung cancer and IMT." (PMID 38787978, 2024). "This case provides further evidence for the existence of RET rearrangements in ALK-positive lung cancer and their potential treatment response to a combination of ALK inhibitors and pralsetinib." (PMID 38698976, 2024). "One of the most successful examples in lung cancer survival is seen in NSCLC patients harbouring the oncogenic fusion between echinoderm microtubule-associated protein-like 4 (EML4) and anaplastic lymphoma kinase (ALK)." (PMID 39695132, 2024). "In conclusion, our retrospective study indicates that adjuvant alectinib is a promising therapeutic strategy for improving DFS in patients with ALK-positive lung cancer and has a favorable safety profile." (PMID 39497711, 2024). "The patient began crizotinib treatment for ALK-positive lung cancer, but metastasis increased in the left axillary and right mediastinal metastatic lymph nodes; the patient’s disease progressed after 4 weeks of treatment." (PMID 38398169, 2024). "As subsequent molecular profiling identified an ALK rearrangement, the study proposed the IGF-1R–IRS-1 signaling axis as a potential therapeutic focus in ALK+ lung cancer, providing insights for upcoming clinical trials." (PMID 38397899, 2024). "This panel, which was specifically designed for the detection of 63 known lung cancer-specific fusion genes, including ALK, RET, and ROS1 fusion genes, successfully identified SLC45A-ROS1 fusions in two patient samples." (PMID 38472960, 2024). "Echinoderm microtubule-associated protein-like 4 (EML4)–anaplastic lymphoma kinase (ALK) oncogenic fusion proteins are found in approximately 5% of non–small cell lung cancers." (PMID 38458397, 2024). "In 2007, the ALK gene rearrangement in NSCLC patients revealed the initial fusion between echinoderm microtubule-associated protein-like 4 (EML4) and ALK in lung cancer." (PMID 38397899, 2024).
lung cancer (continued). "We have also previously reported a case of metastatic ALK-positive lung cancer with poor PS and brain herniation, in which the patient responded remarkably to alectinib after brain tumor resection." (PMID 39759653, 2024). "According to a Japanese study, FGFR3 overexpression mediates ALK-inhibitor resistance in lung cancer." (PMID 39518064, 2024). "There is a lack of real‐world data in Asian populations for brigatinib, a next‐generation anaplastic lymphoma kinase (ALK) inhibitor for patients with non‐small cell lung cancer (NSCLC)." (PMID 39030811, 2024). "Adenocarcinoma with positive anaplastic lymphoma kinase (ALK) rearrangement accounts for 3-7% of lung cancer cases." (PMID 39267820, 2024). "As a result, the study cohort was identified using the diagnosis of lung cancer and treatment with ALK TKIs to identify patients with advanced ALK-positive NSCLC." (PMID 39851929, 2024). "Currently, there are FDA-approved targeted therapies for lung cancers with mutations and genomic alterations in EGFR, ALK, ROS-1, NTRK, MET, RET, HER2, and BRAF." (PMID 39272844, 2024). "The median time between lung cancer diagnosis and start of therapy with an ALK inhibitor was 2.9 months." (PMID 39693368, 2024). "The study suggests exploring this combination further in clinical settings for ALK+ lung cancer patients." (PMID 38397899, 2024). "To validate the impact of rutin on the anticancer activity of ensartinib, we assessed the effect of combining rutin with ensartinib on the ALK-sensitive lung cancer cell line NCI-H3122." (PMID 38789868, 2024). "First, immunohistochemical interrogation of 89 EGFR-mutant, 51 KRAS-altered, and 46 ALK-rearranged lung cancer specimens unveiled that YY1 was ubiquitously expressed in malignant cells at an elevated level relative to the normal epithelium." (PMID 39604408, 2024). "Research has found an interesting phenomenon: in lung cancer patients under 50 years old, there is a higher proportion of lung cancer with targetable genomic changes, such as EGFR mutations, ALK or ROS1 fusions, or ERBB2 insertions." (PMID 38756780, 2024). "This study presents the safety and efficacy of patients receiving Lorlatinib in the second line and beyond for ALK- positive lung cancer in a resource-constrained settings." (PMID 39516655, 2024). "Clinical confirmation of the EMT phenomenon is provided by cases of patients described in the literature in whom the transformation of ALK+ lung cancer into other histological subtypes of lung cancer has been proven." (PMID 39457620, 2024). "We used the CYFRA21‐1:CEA ratio to avoid the effect of cutoff values and found that the ratio was higher in ALK‐positive compared with EGFR‐positive lung cancer." (PMID 38400801, 2024). "Of patients who received additional lung cancer treatments post first-line, n = 73 received two or more ALK TKIs, while n = 39 received only one ALK TKI." (PMID 39851929, 2024). "In lung cancer, the major histologic type associated with an EGFR or ALK mutation is adenocarcinoma." (PMID 38398169, 2024). "Crizotinib exhibits notable efficacy in ALK+ lung cancers, but variable responses and acquired resistance pose challenges." (PMID 38397899, 2024). "In the present study, more ALK‐positive lung cancers were CYFRA21‐1‐positive with higher CYFRA21‐1:CEA ratios compared with EGFR‐positive lung cancers." (PMID 38400801, 2024). "Our results showed that selected patients with lung cancer brain metastases and EGFR mutations or ALK translocations derived clinical benefit from Atezolizumab, Bevacizumab, Carboplatin, and Paclitaxel treatment despite high toxicity rates." (PMID 38610927, 2024). "In this case report, we provide evidence of a novel ALK fusion, XPO1-ALK (intergenic), identified by next-generation DNA sequencing in a patient with advanced lung cancer." (PMID 39911820, 2024).
lung cancer (continued). "In the eXalt3 randomized clinical trial, ensartinib was evaluated as a new first-line treatment option for patients with ALK-positive nonsmall cell lung cancer (NSCLC)." (PMID 38787978, 2024). "ALK gene rearrangements are present in a small subset of lung cancers, primarily in NSCLC adenocarcinomas." (PMID 39671082, 2024). "The database contained 149 ALK‐positive lung cancer patients and analyses were performed on 134 patients with advanced or recurrent ALK‐positive lung cancer, which excluded recurrence‐free cases and comutations with EGFR." (PMID 38400801, 2024). "Since then, various ALK fusion partners have been discovered, and treatment with ALK inhibitors is noticeably effective for ALK fusion gene-positive lung cancer." (PMID 39781173, 2024). "The anaplastic lymphoma kinase (ALK) gene fusion occurs in approximately 3% to 7% of nonsmall cell lung cancer (NSCLC), in which occurs approximately 23% to 31% of brain metastasis patients in poor prognosis." (PMID 38241569, 2024). "While Lorlatinib has emerged as a preferred treatment for ALK-positive lung cancer, its high cost often prevents many patients in low- to middle-income countries (LMICs) from accessing it." (PMID 39516655, 2024). "Currently, ctDNA research is focused on analyzing multiple mutation information, including EGFR, ALK, and KRAS, to assess the prognosis and disease recurrence of lung cancer patients." (PMID 38561776, 2024). "It is not clear why TKI efficacy is worse in CYFRA21‐1‐positive ALK lung cancer, but this will need to be examined in future studies, because many ALK‐positive lung cancers are positive for CYFRA21‐1, as shown in our study." (PMID 38400801, 2024). "We present the case of a 34‐year‐old Japanese man with anaplastic lymphoma kinase (ALK)‐positive non‐small cell lung cancer and brain metastases." (PMID 38924375, 2024). "This phosphorylation notably promotes tumor growth in ALK+ lung cancer cells, a finding supported by a phosphoproteomic analysis delineating downstream pathway involvement." (PMID 38397899, 2024). "ALK rearrangement and STK11 gene mutation are also associated with VTE in patients with lung cancer." (PMID 38890693, 2024). "The cell proliferation assay showed alectinib exerts potent activity in ALK1510-c4 cells established from an ALK+ lung cancer patient." (PMID 39551860, 2024). "In a study of a patient with anaplastic lymphoma receptor tyrosine kinase (ALK) fusion-positive lung cancer who had developed TKI resistance, combined ALK and IGF-1R inhibition improved therapeutic efficacy." (PMID 38540176, 2024). "Lung cancer is a prevalent malignancy, and those with specific molecular genetic alterations in the ALK, BRAF, or EGFR genes have been endorsed by the US Food and Drug Administration (FDA) as first-line targeted therapies." (PMID 39555099, 2024). "Non‐small‐cell lung cancer (NSCLC) accounts for approximately 85% of lung cancer patients, with anaplastic lymphoma kinase (ALK) rearrangements occurring in approximately 3%–7% of NSCLC patients." (PMID 39555835, 2024). "The ALK fusion oncogene is present in 3%–5% of non-small cell lung cancers, with the majority of lung cancers carrying the gene being adenocarcinoma (97%)." (PMID 38605928, 2024). "On the other hand, a study explored the potential of co-targeting ALK+ lung cancer cells with alectinib and the SHP2 inhibitor SHP099." (PMID 38397899, 2024). "In the presented case, the ALK double fusion of LOC399815–ALK (L5: A20) of ALK-EML4 (A3: E7) in peripheral blood ctDNA of a lung cancer patient with brain metastasis was detected by NGS." (PMID 38241569, 2024). "It has also been recommended that Pemetrexed be used in patients with ALK-translocated lung cancer based on first-line, pre-TKI context evidence." (PMID 38610927, 2024). "Src has also been identified as a key molecule in conferring resistance to specific treatments in ALK-rearranged lung cancer." (PMID 38921583, 2024).